Y_RNA (Y RNA )
Gene: Miscellaneous RNA gene on chromosome 6 (137,784,374 to 137,784,486, forward strand). Ensembl gene ENSG00000207300.
Homologues: Orthologues: chimpanzee Y_RNA (100% identical). Paralogues in human: RNY1 (85% identical), Y_RNA (85% identical), Y_RNA (84% identical), Y_RNA (83% identical), Y_RNA (82% identical), Y_RNA (81% identical), RNY1P8 (81% identical), RNY1P11 (80% identical), RNY1P7 (80% identical), Y_RNA (80% identical), Y_RNA (79% identical), Y_RNA (78% identical), and 95 more.